CRP (C-reactive protein)
Diseases named in the same sentence as CRP in open-access papers (continued):
Sharing a sentence is not in itself a finding about the gene and the disease.
Sepsis (continued). "Knowing the factors influencing CRP levels in sepsis as well as the patterns of these levels associated with different medical or surgical conditions can lead to a better understanding of its diagnostic value." (PMID 17598889, 2007). "C-reactive protein, IL-6 and lipopolysaccharide-binding protein appear to be superior to procalcitonin as diagnostic markers for infection and sepsis in patients admitted to a Department of Internal Medicine." (PMID 16569262, 2006). "Several studies have focused on the diagnostic test abilities of CRP in diagnosing infection and/or sepsis." (PMID 16569262, 2006). "Therefore, it is of interest to compare the diagnostic accuracy of PCT and CRP in 284 emergency patients with suspected sepsis, using Sepsis-3 criteria and ROC analysis within 2 hours of presentation." (PMID 42282342, 2026). "Importantly, neutrophil H4K5la on day 1 served as an independent predictor of sepsis, and its combination with C-reactive protein (CRP) significantly improved diagnostic accuracy." (PMID 41491598, 2026). "The diagnostic accuracy of LBP for sepsis was similar to that of CRP but lower than that of PCT." (PMID 41597433, 2026). "Additionally, the analysis identified several factors associated with an increased risk of postoperative sepsis, including advanced age, female sex, elevated BMI, positive preoperative urine culture, and higher postoperative CRP and FPG levels." (PMID 40761819, 2025). "Postoperative CRP levels on both days 3 (OR = 8.246, 95% CI: 1.564-49.302, P < 0.001) and 5 (OR = 5.268, 95% CI: 1.035-28.124, P < 0.001) were also significant indicators of sepsis risk." (PMID 40761819, 2025). "However, a sharp rise in CRP levels is not only a diagnostic parameter in sepsis patients, but is involved in killing bacteria through opsonization with complement activation and cell lysis." (PMID 41145817, 2025). "This may be interpreted as proving that CRP is most useful for the diagnosis of sepsis and the least for grading sepsis severity among the diagnostic criteria utilized (Henriquez-Camacho and Losa, 2014), unlike lactate (Kang and Park, 2016)." (PMID 39857101, 2025). "In examining patients with only complete data, excluding CRP (n = 115 patients), only lymphopenia (OR 6.55; 95 % CI 2.34–20.90) and a length of stay greater than 14 days (OR 10.63; 95 % CI 2.94–50.46) were associated with sepsis development (Tables e2 and e3)." (PMID 40555121, 2025). "CD64% achieved 92.8% sensitivity and 90.8% specificity, respectively; these results come in line with other reported study results regarding the valuable role of CD64 as an early diagnostic neonatal sepsis marker, especially when combined with other acute phase reactants as CRP measurement." (PMID 40224545, 2025). "Bivariate analysis revealed that advanced age (P = 0.042), a history of hospitalization in the last 6 months (P = 0.02), the presence of sepsis (P = 0.023), low hemoglobin levels (P <0.001), and elevated CRP levels (P = 0.006) were significantly associated with death." (PMID 40230497, 2025). "However, patients with sepsis and underlying liver cirrhosis have reduced CRP levels due to impaired hepatic synthesis of this acute-phase protein." (PMID 39997462, 2025). "Therefore, the present study was designed to compare the temporal trends and diagnostic accuracy of PCT, CRP, and IL-6 in detecting early postoperative sepsis following lung decortication." (PMID 41281040, 2025). "Therefore, markers such as white blood cell count, C-reactive protein, tumor necrosis factor, IL-1, and IL-6 are commonly used as auxiliary diagnostic indicators for sepsis in clinical practice." (PMID 40540505, 2025). "The CRP/Alb ratio has recently been used as a predictor of prognosis in patients with severe sepsis or septic shock; elevated CRP/Alb ratio at admission has been associated with a higher mortality rate in adult patients with sepsis." (PMID 40573094, 2025). "•Diagnostic accuracy of CRP in sepsis is limited by high heterogeneity." (PMID 41429071, 2025).
Sepsis (continued). "Notably, CRP levels > 100 mg/L after postoperative day 4 had a high association with the presence of an infection or sepsis in their cohort." (PMID 41153812, 2025). "Our analysis reveals three core insights: First, biomarker mechanisms are now well-defined across species, with diagnostic tools like CRP in canine sepsis, prognostic indicators such as cfDNA in oncology, and predictive signatures like BRAF in melanoma enabling more targeted interventions." (PMID 41227463, 2025). "In addition, the highest values of procalcitonin were in sepsis caused by K. pneumoniae and CRP in sepsis caused by A. baumannii." (PMID 39417064, 2024). "Future studies should clarify whether infection-specific transcriptional pathways of granulocytic differentiation exist that differentiate sepsis from other causes of stress-induced granulocytosis more reliably than CRP." (PMID 39434093, 2024). "Peak C-reactive protein was positively associated with increased sepsis mortality (P < .001)." (PMID 38680606, 2024). "All epigenetic marks demonstrated good diagnostic capability for sepsis, surpassing CRP." (PMID 39926115, 2024). "Higher GCS and CRP levels were associated with sepsis in the geriatric polytrauma group." (PMID 38541796, 2024). "SHAP results revealed that older age, higher respiratory rate, procalcitonin, neutrophil–lymphocyte count ratio, C-reactive protein, plaque, leukocyte particle concentration, as well as lower oxygen saturation, systolic blood pressure, and hemoglobin levels increased the risk of sepsis." (PMID 38472930, 2024). "Studies have confirmed that CRP levels have a minimal association with the disease severity in sepsis, whereas they serve as the most commonly used biomarker for predicting the disease severity in patients with pancreatitis, with 100% and 81.4% sensitivity and specificity, respectively." (PMID 38247605, 2024). "Thus, there is evidence of the role of CRP and platelet count in the diagnostic and prognostic evaluation of sepsis." (PMID 39006693, 2024). "IL-6 and PCT have a similar, yet superior, diagnostic value for sepsis compared to CRP." (PMID 39589972, 2024). "Thirty-one studies analyzed by us have shown that an increased MDW value is associated with a higher risk of sepsis and that its combination with clinical parameters (such as qSOFA) and other biomarkers (CRP, PCT) can enhance diagnostic sensitivity and risk stratification capacity." (PMID 39852198, 2024). "Additionally, extracorporeal circulation time, BMI, elevated perioperative peak serum C-reactive protein concentration, reduced renal perfusion, and perioperative sepsis have been identified as risk factors for AKI development." (PMID 39439591, 2024). "Moreover, MD can decrease the risk of sepsis and respiratory infections, and inflammation, as implied by a decrease in CRP and proinflammatory cytokines." (PMID 38390861, 2024). "The association between neonatal sepsis outcomes and age, sex, CRP, and blood culture (N = 71)." (PMID 38654771, 2024). "It is known that on one hand, higher C-reactive protein and IL-6 levels have been associated more with Gram(−) bacteria than Gram(+) bacteria, inducing greater inflammation and thus raising concern regarding the treatment of Gram(−) sepsis." (PMID 38543060, 2024). "In addition, our study confirmed that the morphologic parameters, especially NeuY-, have higher diagnostic predictive power for sepsis compared to CRP." (PMID 38337856, 2024). "Some studies have identified elevated CRP levels as a risk factor for developing sepsis." (PMID 38684973, 2024). "C-reactive protein/serum albumin ratio and the quick Pitt bacteremia score are two useful tools for clinicians to assess severity and predict mortality risk in patients with sepsis attributable to bloodstream infections." (PMID 39252713, 2024). "This indicates that PCT and CRP may offer more limited predictive value for the early identification of sepsis risk." (PMID 39655134, 2024).
Sepsis (continued). "Therefore, the present study comprehensively investigates the diagnostic and prognostic value of the CRP compared to the PCT in patients admitted to an internistic ICU with sepsis or septic shock." (PMID 37204560, 2024). "We analyzed whether CRP, procalcitonin, and presepsin were associated with survival in the sepsis group." (PMID 36832265, 2023). "WBC, PCT, and CRP are commonly used diagnostic and prognostic biomarkers for sepsis." (PMID 37904138, 2023). "Despite these limits as a diagnostic marker of sepsis, CRP can be used to exclude sepsis." (PMID 37627653, 2023). "In the UK Biobank cohort (N = 486,484, including 11,643 with sepsis), IL6R blockade was associated with a decreased risk of our primary outcome, sepsis (odds ratio (OR) = 0.80; 95% confidence interval (CI) 0.66 to 0.96, per unit of natural log-transformed CRP decrease)." (PMID 36716318, 2023). "However, in previous studies, we were unable to find any MR studies examining the relationship between gut microbiota, sepsis, and their association with CRP." (PMID 37662942, 2023). "C-reactive protein levels were found to be significantly associated with a poor sepsis outcome." (PMID 37252936, 2023). "There is evidence that persistently high CRP and the necessity for ICU admission are independent risk factors for the emergence of post-COVID conditions, and there is an association between a faster reduction of CRP and lower one-year mortality after sepsis and pneumonia." (PMID 37513836, 2023). "Combining CRP with the quick sequential organ failure assessment (qSOFA) probably improves the accuracy of qSOFA alone in identifying patients at risk of dying in hospital from sepsis." (PMID 37744876, 2023). "Nonetheless, due to the insufficient research on the relationship between gut microbiota and serum inflammation, we examined the effect of CRP, an inflammation protein linked to a higher risk of infections in adults, in the association between gut microbiota and sepsis." (PMID 37662942, 2023). "Underlying diseases may affect the levels of biomarkers in sepsis, and, e.g., CRP is low in patients with liver cirrhosis." (PMID 38139346, 2023). "However, one theoretical concern of CRP reducing therapies is the potential risk of immunosuppression, especially in bacterial infections and sepsis, given CRP's well‐described role in the innate immune response." (PMID 36468184, 2023). "Contrarily, in our SIRS/sepsis cohort, sCD137 was negatively associated with serum CRP levels." (PMID 38139346, 2023). "Therefore, we conducted multiple MR analyses based on genome-wide association study (GWAS) summary statistics to evaluate the causal association among gut microbiota, CRP, and sepsis." (PMID 37662942, 2023). "A follow-up study of sepsis survivors identified a hyperinflammation/immunosuppression phenotype with a significantly higher 1-year mortality risk, demonstrated by CRP as a marker of ongoing inflammation and additional markers of immunosuppression including soluble PD-L1." (PMID 38042792, 2023). "Therefore, the association of circulating chemerin and CRP with sepsis severity is influenced by the underlying disease." (PMID 37509420, 2023). "However, in another study, the diagnostic accuracy of MR-proADM for sepsis detection was inferior to clinically used biomarkers (CRP, PCT, and IL-6), and the combination of MR-proADM with any of these markers did not improve diagnostic accuracy." (PMID 37626802, 2023). "In contrast to Yamamichi, most scholars believe that PCT is significantly superior to CRP in the diagnostic sensitivity and specificity of severe sepsis and septic shock, and is also superior to CRP in the assessment of the severity and prognosis of the disease." (PMID 35346141, 2022). "A CRP test may be used to find or monitor conditions that cause inflammation, such as sepsis, bowel disease, lupus or rheumatoid arthritis, and osteomyelitis." (PMID 35049659, 2022).
Sepsis (continued). "PCT and CRP have gained high distinction in clinical settings among the biomarkers of interest due to their high diagnostic values for inferring bacterial infection and sepsis." (PMID 35149284, 2022). "Based on sensitivity and strong negative predictive value inneonatal sepsis, measurement of CRP after 48 hours reveals higher sensitivity and NPV than earlier measurement, demonstrating that CRP 2 is a good diagnostic tool for ruling in sepsis and ruling out sepsis." (PMID 37654832, 2022). "Finally, the limits showed that CRP remains a widely used diagnostic and therapeutic biomarker in sepsis to date, mainly because a decrease in its values correlates with the success of antimicrobial treatment." (PMID 35741168, 2022). "However, some studies have shown that the diagnostic value of CRP alone in sepsis is only moderate, and the predicting positive blood culture and disease prognosis are lower than that of procalcitonin and sTREM-1." (PMID 35991149, 2022). "Complete blood count and complete metabolic panel were normal (e.g. WBC 9.42 109/L [4.0–10.0]; CRP 5.03 mg/l [0.00–10.00]; procalcitonin 0.02 ng/ml [< 0.5 ng/ml—low risk of severe sepsis and/or septic shock; > 2.0 ng/ml—high risk of severe sepsis and/or septic shock]." (PMID 34983474, 2022). "The authors could demonstrate that the diagnostic accuracy of sDLL1 for the identification of sepsis is superior compared to the established biomarkers, namely CRP, leukocytes, and procalcitonin (PCT)." (PMID 35922468, 2022). "C-reactive protein, an infectious inflammatory biomarker, may complement the evaluation of clinical signs and risk factors within the diagnosis of sepsis—several studies have shown its applicability in precocious diagnosis as the test is easily available." (PMID 36467887, 2022). "The association observed in our study could therefore originate in both the underlying inflammation accompanying complications predisposing to AKI, especially sepsis, but also the intrinsic capacity of CRP to exacerbate local inflammation in the kidney." (PMID 35203472, 2022). "Elevated serum CRP concentration indicates a potential risk of organ failure and sepsis." (PMID 34281552, 2021). "GDF-15 level in severe sepsis was significantly associated with organ dysfunction markers such as creatinine (kidney) and bilirubin (liver), and disease severity markers such as lactate, hs-CRP, APACHE II score and SOFA score." (PMID 34441955, 2021). "Additionally, the expression of EV-associated CRP in the blood of sepsis patients is reported to be higher compared to blood EVs from critically ill, non-septic patients." (PMID 34451925, 2021). "Moreover, the MeD was found to decrease inflammation, with a reduction in C-reactive protein (CRP) and proinflammatory cytokines, as well as a reduction in the risk of respiratory infections and sepsis." (PMID 34069656, 2021). "Compared to other biomarkers used for this purpose (procalcitonin, C-reactive protein) it is hypothesized to be more specific for sepsis, as it is directly implicated in the pathogenesis of the syndrome." (PMID 34150378, 2021). "Moreover, CRP has been found to have a moderate role in sepsis diagnosis and procalcitonin has higher diagnostic accuracy than CRP." (PMID 35199783, 2021). "Although there is insufficient evidence currently supporting the overall diagnostic accuracy compared with PCT or CRP, presepsin may still have advantages for early screening of sepsis, which is a good sign for development for new biomarkers." (PMID 34630395, 2021). "We further analyzed the significant variables using multivariate logistic regression with known risk factors (age, %TBSA, and presence of inhalation burns), which revealed that the odds ratio [95% CI] for IG% (1.09 [1.00–1.08]) and CRP (1.02 [1.03–1.08]) were significantly associated with sepsis." (PMID 34915849, 2021).
Sepsis (continued). "However, the traditional clinical signs of infection and routine laboratory tests for sepsis, such as CRP or WBC, are known to have insufficient diagnostic accuracy." (PMID 33420845, 2021). "When using progranulin as a biomarker for sepsis and pneumonia, the diagnostic performance of this molecule is comparable to that of procalcitonin, and surpasses the other established biomarkers C-reactive protein and interleukin-6 with regard to sensitivity and specificity." (PMID 34476621, 2021). "Interestingly, an inverse relationship has been observed in sepsis cases where a decreased expression of the HLA-DR marker on monocytes was associated with persistently increased CRP concentration over time." (PMID 33794783, 2021). "Therefore, the aim of the present study was to evaluate the association of baseline serum PCT and CRP levels and mortality, among patients with sepsis and septic shock, with a respiratory source of infection." (PMID 33810263, 2021). "Plasma CRP > 62.8 mg/L is an optimal cutoff value for predicting high risk of death from sepsis." (PMID 34439240, 2021). "Monitoring of C-reactive protein/albumin level in a patient admitted to intensive care unit could be useful for stratifying patients with a high risk of developing sepsis." (PMID 35199783, 2021). "Overall, PSEP had a better diagnostic accuracy for sepsis and septic shock compared to CRP and PCT." (PMID 34068959, 2021). "Studies have shown that high CRP levels may be a risk factor for acute kidney injury in sepsis, but initial CRP cannot be used as an indicator to predict the prognosis of patients with sepsis." (PMID 34233608, 2021). "Despite a lack of larger studies demonstrating an association between TLR4 and biomarkers like PCT and CRP in diagnosis of sepsis, results of a recent study conclude the possibility of using TLR2 and TLR4 expression to determine the severity of sepsis as a diagnostic biomarker (p < 0.05)." (PMID 33803628, 2021). "There are hundreds of biomarkers associated with sepsis, but very few (e.g., C reactive protein and procalcitonin) are currently used as a clinical routine, indicating that we might lack knowledge about how sepsis regulates gene expression." (PMID 34680414, 2021). "Sepsis is a systemic inflammatory response syndrome caused by infection that is assessed usually by measuring body temperature, peripheral white blood cell count, percentage of neutrophils, CRP level, and organ function." (PMID 34722573, 2021). "CRP is an inflammatory biomarker, and a high level of CRP in the blood may be a sign of sepsis caused by severe infections." (PMID 34567660, 2020). "Increased inflammatory parameters, namely CRP and white blood cell count, advanced age, particularly over the age of 80, as well as a diagnosis of sepsis are independent risk factors for death and could be used as predictive markers of poor outcome in CDI." (PMID 32895405, 2020). "Besides, we also explored other independent factors predicting risk of mortality in sepsis patients, and observed that apart from miR‐125b, Scr, CRP level, and SOFA score correlates with increased mortality risk as well." (PMID 31696556, 2020). "Other studies have indicated that while CD64 may be a useful biomarker for sepsis diagnosis, it is best combined with other biomarkers such as CRP, PCT or sTREM-1 to increase overall diagnostic power." (PMID 32164268, 2020). "Additionally, TNFR1 performed better than CRP in predicting 30-day mortality and thus can potentially identify high risk patients with sepsis." (PMID 32948801, 2020). "The pooled sensitivity and specificity of neutrophil CD64 were 0.87 (95% CI, 0.80–0.92) and 0.89 (95% CI 0.82–0.93), which support the idea that CD64 might be a better diagnostic tool for sepsis then procalcitonin and CRP." (PMID 33198109, 2020). "Furthermore, 4 studies analyzed the diagnostic accuracy of CRP for sepsis; the pooled Sen and Spe were 0.77 (95% CI 0.73–0.81) and 0.71 (95% CI 0.29–0.94), respectively." (PMID 33292630, 2020).